BMP7 (bone morphogenetic protein 7)
Diseases named in the same sentence as BMP7 in open-access papers (continued):
Sharing a sentence is not in itself a finding about the gene and the disease.
glioma (13 papers, 2014 to 2024). A benign or malignant brain and spinal cord tumor that arises from glial cells (astrocytes, oligodendrocytes, ependymal cells). "We then assessed the combined impact of H3.3K27M expression and exposure to BMP7 on the invasive properties of glioma cells using a Matrigel-coated transwell assay." (PMID 39373720, 2024). "First, BMPs—particularly BMP2, BMP4, and BMP7—are highly expressed in glioma tumors, suggesting a rather pro-oncogenic role." (PMID 38542334, 2024). "In most of the studies, BMP7 has also been elucidated an anti-proliferation and anti-survival role in glioma by its growth inhibitory and differentiation inducer activity." (PMID 34357080, 2021). "This antiproliferative property of BMP7 has been further corroborated by in vivo optical imaging of luciferase-tagged glioma-derived cells that have been intracranially implanted in mice." (PMID 34012965, 2021). "In vitro co-culture results showed that the BMP7-overexpressing NT2 cells hampered the migration of C6 glioma cells, which highlights the potential of NT2 cell-based delivery of hBMP7 for impeding the metastasis of glioma cells." (PMID 32106545, 2020). "This would be in line with a previous report showing that BMP7 decreases proliferation of a glioma cell line through cell cycle arrest in the G1 phase, through the modulation of CDK2, CDKN1A and pRB expression." (PMID 25860932, 2015). "In a previous work, we synthesized controlled release microspheres optimized for intracranial delivery of BMP7, and showed that these devices are able to stop the in vitro growth of a glioma cell line." (PMID 25860932, 2015). "These microspheres were able to release BMP7 for more than two months, and this released protein was able to stop the in vitro growth of a glioma cell line model." (PMID 25860932, 2015). "The optical imaging study further provided direct evidence of BMP7-induced cell cycle arrest in glioma model." (PMID 26546412, 2015). "Additional studies employing larger microarray databases available nowadays should confirm the view that the role of BMP4 and BMP7 in glioma differs from that of BMP2." (PMID 24877113, 2014). "BMP7 induces a specific transcriptomic and phenotypic switch in a H3.3K27M mutant glioma context." (PMID 39373720, 2024). "Likewise, BMP7 has been shown to inhibit tumor proliferation by arresting glioma-derived cells in the G1 phase of cell cycle." (PMID 34012965, 2021). "Thus, the dual regulatory role of BMP7 in glioma that dissociates the invasion capability from tumorigenicity has been proposed, but their detailed and precise mechanism in glioma development needs to be further explored and examined." (PMID 34357080, 2021). "Increasing evidence strongly supports a key role for BMP7 as a glioma growth inhibitor." (PMID 25860932, 2015). "Recent evidence has shown the tumor-suppressive effect of BMP-7 in glioma-derived cells." (PMID 24658029, 2014). "Indeed, using a genetically engineered glioma model, we confirmed that BMP7 is sufficient to potentiate the entry of cells in a quiescent state in a H3.3K27M-dependent manner, via a transcriptomic switch largely relying on the downregulation of E2F-targets cell-cycle regulating genes." (PMID 39373720, 2024). "Thus, the growth factors, e.g., BMP4 and BMP7, which present and play a role in the neuron differentiation and development have been suggested to be of importance for glioma recurrence and these factors should be further investigated for future pharmaceutic targets." (PMID 34357080, 2021). "In the PDGF-driven TV-A rat tumors, the glioma-related genes IGFBP2 and BMP7 were uniquely under-expressed compared to the other three species." (PMID 29352201, 2018). "GREM-1 overexpression in glioma cell lines also promoted epithelial to mesenchymal transition (EMT) through upregulated expression of E-Cadherin and BMP7, and activation of TGF-β signaling through engagement of BMP receptors I and II." (PMID 29435175, 2018).
glioma (continued). "In a glioma cell line (Gli36ΔEGFR-LITG) that overexpresses EGFR, they observed that BMP7 treatment decreased proliferation up to 50% through cell cycle arrest in the G1 phase but not by induction of apoptosis." (PMID 24877113, 2014). "Interestingly, BMP7 is the top down-regulated gene in GSCs that proves resistant to TMZ, the DNA alkylating agent used as a first line of treatment in gliomas." (PMID 34012965, 2021). "We described that BMP7 promotes astrocytic differentiation of glioma-initiating cells by inducing the expression of the EMT transcription factor SNAIL in a SMAD1/5-dependent manner; the induction of Snail is required for BMP7 to be able to induce the expression of GFAP, an astrocytic marker." (PMID 38256140, 2024). "RNAseq on glioma cell lines exposed or not to BMP7 are available on GEO (GSE268576)." (PMID 39373720, 2024).
colon cancer (11 papers, 2016 to 2024). "BMP7 is widely expressed in many tumors including breast, prostate, and colon cancer, and it is implicated in the regulation of cell proliferation." (PMID 31591478, 2020). "BMP7 is mostly expression in tumor including colon cancer, and it is regulated of cell proliferation." (PMID 35560163, 2022). "For example, resveratrol inhibits the PI3K-Akt signaling pathway by upregulating BMP7, thus promoting the apoptosis of colon cancer cells and suppressing the proliferation of colon cancer cells." (PMID 34194536, 2021). "Using the MC38 immunogenic colon cancer model, BMP7-expressing and control tumors were grown in the flanks of C57BL/6 mice treated with anti-PD-L1 or isotype control antibody, and examined for CD8+ T cell infiltration at 5 weeks post-inoculation." (PMID 32117236, 2020). "In vivo, the expression of BMP7 in murine breast and colon cancer models led to the significant decrease in abundance of tumor-infiltrating CD8+ T cells." (PMID 32117236, 2020). "In colon cancer, BMP7 is common overregulated gene, as are TGFB2, TGFBI, and TGIF2, which might be involved in the regulation of SOX4." (PMID 39228892, 2024). "In these KRAS-dependent colon cancer cells, KRAS activates bone morphogenetic protein 7 (BMP-7) signaling, leading to TAK1 activation, β-catenin nuclear localization and transcriptional upregulation of Wnt target genes." (PMID 29652830, 2018). "Conversely, bone morphogenetic protein 7 (BMP-7) maintained the endothelial phenotype, inhibited endo-MT and progression of cardiac fibrosis, renal injury, and colon cancer." (PMID 26828526, 2016). "In addition, we have also measured the effect of CHST15 siRNA on the expression of EMT markers such as E-cadherin, vimentin, BMP7 and Wnt3 using TGF-β-stimulated colon cancer cell line and identified a significant suppression of these markers in the CHST15 siRNA treated cells." (PMID 27410685, 2016).
Hyperglycemia (10 papers, 2011 to 2024). An increased concentration of glucose in the blood. "During the development of DN, hyperglycemia causes oxidative stress and leads to BMP-7 expression decrease in renal cells." (PMID 22474533, 2012). "Our BMP-7 data showed a significant decrease in hyperglycemia, systemic hyperlipidemia, and cholesterol uptake genes." (PMID 36829889, 2023). "Recent studies indicated that bone morphogenetic protein-7 (BMP-7) upregulated the expression of endogenous SnoN against renal TIF induced by TGF-β1 or hyperglycemia." (PMID 35314669, 2022). "In conclusion, our previous pre-diabetic and Type-1 diabetic muscle studies suggested BMP-7 decreases hyperglycemia as shown in graphical abstract." (PMID 34685620, 2021). "In recent years, a large number of studies have found many differentially expressed proteins in the state of hyperglycemia, including bone morphogenetic protein 7, lactoferrin, albumin, cathepsin D, etc.." (PMID 34957219, 2021). "In brief, the current results with PRDM16 and BMP7 suggest that brown/beige adipogenesis is increased in response to an exposure to maternal hyperglycemia." (PMID 27340502, 2016). "Treatment of diet-induced obese C57Bl6/J mice with BMP7 led to an improved metabolic phenotype, consisting of a decreased fat mass and liver lipids as well as attenuated dyslipidemia and hyperglycemia." (PMID 24066098, 2013). "Of note, treatment of diet-induced obese C57Bl6/J mice with BMP7 diminished fat mass and liver lipid content and attenuated dyslipidemia and hyperglycemia." (PMID 24066098, 2013). "Expression or treatment with recombinant BMP-7 has been shown to improve renal damage from hyperglycemia-induced oxidative stress in the kidney of diabetic animals." (PMID 22474533, 2012). "In addition, BMP7 lowered plasma TG (−25%, P<0.05) and total cholesterol levels (−10%, P<0.05), and diminished hyperglycemia (−27%, P<0.01)." (PMID 24066098, 2013). "BMP-7 improves renal damage from hyperglycemia-induced oxidative stress in the kidney of diabetics." (PMID 21876712, 2011). "In the current study, we tested in two independent birth cohorts whether the fetal exposure to maternal hyperglycemia is associated with placental DNA methylation variations in genes involved in BAT/wBAT genesis, specifically targeting the PRDM16, BMP7, CTBP2, and PPARGC1α gene loci." (PMID 27340502, 2016). "In conclusion, we speculated that BMP-7 could upregulate SnoN mRNA level by activating the classical Smad1/5 signaling pathway, and it also could reduce the ubiquitination of SnoN protein, finally restoring the SnoN protein level to inhibit hyperglycemia-mediated renal tubular epithelial fibrosis." (PMID 35314669, 2022). "We also observed that control of hyperglycemia may improve renal function and reverse renal BMP-7 expressions at the initial stage of DN but not at the late stage of DN in type-1-like diabetic rats." (PMID 21876712, 2011).
kidney damage (10 papers, 2009 to 2023). "BMP7, a renal tubular growth morphogen, has recently been shown to help maintain renal function and reduce kidney damage." (PMID 36945919, 2023). "Likely also due to the high cost reported for BMP-7-based products, more recent research in the context of nephropathy has been focused on more indirect ways to achieve BMP-7 agonism and/or TGF-β antagonism." (PMID 37626268, 2023). "As a result, crocin and losartan can reduce kidney damage and improve kidney function by reducing ROS and increasing endogenous BMP7 expression." (PMID 36945919, 2023). "Previous studies have shown lower BMP-7 levels in several types of kidney damage, both in experimental models and in patients." (PMID 36613483, 2022). "It has been revealed that transforming growth factor (TGF) has an important role in the pathogenesis of kidney damage, and BMP-7 inhibits the biological actions of TGF." (PMID 33235692, 2020). "Recent studies showed that the USAG-1 is abundantly expressed in the kidney, and in kidney injury models, the ratio of USAG-1 to BMP-7 expression decreased with kidney damage but increased after subsequent kidney regeneration." (PMID 19696925, 2009). "Against this background, we hypothesize that an imbalance in BMP-2 and BMP-7 occurs at CKD stages I-III associated with the development of hypertension, vascular stiffness, and progressive kidney damage." (PMID 36613483, 2022). "FERM domain containing 3 (FRMD3) is responsible for maintaining the shape and integrity of nephron cells, and bone morphogenetic protein 7 (BMP7) helps maintain function and reduce kidney damage." (PMID 36945919, 2023).
Stroke (10 papers, 2010 to 2021). Sudden impairment of blood flow to a part of the brain due to occlusion or rupture of an artery to the brain. "Rats that received a single dose of intravenous BMP7 24 h after stroke showed a decrease in body asymmetry and an increase in locomotor activity." (PMID 34390115, 2021). "Another group reported that the intracisternal administration of BMP-7 enhanced functional recovery in a rat model of stroke." (PMID 29922215, 2018). "9cRA -mediated neuroregeneration through BMP7 in stroke brain is further supported by the similar neuroreparative action of BMP7." (PMID 28674431, 2017). "Although BMP2 is upregulated after cerebral ischemia, its function as an endogenous neuroprotectant is controversial since recombinant soluble Noggin, an antagonist of BMP2, BMP4 and BMP7, demonstrates neuroprotective effects in models of stroke." (PMID 24618040, 2014). "In the stroke model of middle cerebral artery occlusion rAAV-transduced v-BMP7 reduced the infarct size in mice." (PMID 24618040, 2014). "In models of ischemic stroke BMP7 reduced the infarct size and improved functional recovery at delayed time points after stroke." (PMID 24618040, 2014). "The pre-stroke implantation of fetal kidney cells, a tissue with high levels of BMP-7, into the rodent cortex reduced infarct volume and improved functional recovery." (PMID 24287916, 2013). "BMP7 was reported to play an important role in facilitating recovery after stroke in rat." (PMID 32450902, 2020). "The antagonistic action of noggin against BMP7 has been documented in stroke brain." (PMID 28674431, 2017). "On the other hand, intraventricular injection of BMP7 reportedly facilitates motor recovery after stroke, although the effect is probably through enhanced proliferation of neural progenitors, which takes place in a much later timeframe than that of the current study." (PMID 26317208, 2015). "Moreover, post-stroke intracisternal or intracerebroventricular BMP-7 injection partially improves motor function two weeks after ischemia in rats." (PMID 24287916, 2013). "Besides its interaction with BMP7, 9cRA may induce trophic responses in stroke brain through other pathways." (PMID 28674431, 2017). "BMP-7, a trophic factor expressed by HMO6 cells, is a member of transforming growth factor-β superfamily, the receptors are found in neuron and astrocytes and known to promote neuroregenerative effect in stroke rats." (PMID 20668522, 2010). "9cRA marginally enhanced the expression of BMP7, but not GDNF or BDNF, in the SVZ of stroke rats." (PMID 28674431, 2017). "However, in vivo administration is limited by the short half-life and the large amounts of biologically active BMP7 that need to be administered (at least 10 mg/kg body weight), which might explain why recombinant BMP7 reduced the infarct volume in some, but not all experimental stroke studies." (PMID 24618040, 2014).
Anophthalmia (9 papers, 2006 to 2021). Absence of the globe or eyeball. "The role of BMP4/7 heterodimers in eye development is likely conserved in humans since Bmp4 or Bmp7 are co-expressed in the developing human eye, and mutations in either gene are associated with anophthalmia, microphthalmia and chorioretinal coloboma." (PMID 31566563, 2019). "Specifically, Bmp7-deficient mice exhibit a variety of orofacial malformations including anophthalmia, mandible anomalies, missing or hypoplastic teeth, and cleft palate." (PMID 23516636, 2013). "Heterozygous BMP7 loss-of-function variants have also been associated with anophthalmia." (PMID 30568244, 2019). "Mutations in the Bmp7 gene can lead to anophthalmia or microphthalmia in mice and humans." (PMID 28546339, 2017). "Anophthalmia, the most severe phenotype, is associated with mutations of the Rax, Sox2, Lhx2, BMP-4, and BMP7 genes." (PMID 31817535, 2019). "Among other BMP family members, BMP7 has been shown to play a pivotal role in eye development during embryogenesis, and BMP7- knockout mice have anophthalmia." (PMID 23799103, 2013). "While mouse BMP7 expression is restricted to the RPE and lens, BMP7 knockout mice display a gobal eye developmental defect manifesting as small eyes and anophthalmia." (PMID 17010201, 2006). "Similarly, mice lacking BMP-7 had severe eye defects including anophthalmia, in addition to kidney and skeletal defects." (PMID 34685584, 2021).
diabetic cardiomyopathy (9 papers, 2016 to 2025). Diabetic cardiomyopathy is a disorder of the heart muscle in people with diabetes. "In the context of diabetic cardiomyopathy, bone morphogenetic protein-7 (BMP-7) alleviated inflammation-induced pyroptosis by inhibiting the TLR4-NLRP3 complex, which is activated by GBP5 and NIMA-related kinase 7 (Nek7)." (PMID 40788157, 2025). "Another study also verified that BMP7 relieves pyroptosis induced by NLRP3 inflammasome in the setting of diabetic cardiomyopathy." (PMID 36858954, 2023). "BMPs (BMP2, BMP4, and BMP7) elicit anti-atherogenic and anti-inflammatory effects, while reducing LV remodeling and preserving cardiac function in diabetic cardiomyopathy." (PMID 37240345, 2023). "To date, few studies have addressed the role of BMPs in cardiovascular diseases, and to our knowledge, this is the first study to assess the therapeutic potential of targeting BMP7 signalling in diabetic cardiomyopathy." (PMID 34690762, 2021). "We and others have recently reported that exogenous bone morphogenetic protein-7 (BMP-7; Osteogenic protein-1; OP-1) inhibits inflammation in pre-diabetic cardiomyopathy." (PMID 34685620, 2021). "The main finding of this study is that a cardiac-selective gene therapeutic approach, designed to overexpress BMP7, offers cardioprotection in a murine model of diabetic cardiomyopathy." (PMID 34690762, 2021). "BMP-7 treatment showed a significant reduction (p < 0.001) in the expression of IL-1β, and IL-18 compared to the diabetic cardiomyopathy." (PMID 34685620, 2021). "BMP-7 treatment showed protective effects against pyroptotic protein expression compared to the diabetic cardiomyopathy, as indicated by a significant reduction (p < 0.001) in caspase-1 levels." (PMID 34685620, 2021). "Additionally, BMP7 alleviates pyroptosis and inflammation and improves cardiac dysfunction in diabetic cardiomyopathy by inhibiting the Nek7/GBP5 signaling axis, thus suppressing inflammasome formation in cardiomyocytes." (PMID 40636987, 2025). "However, it is unknown whether BMP-7 treatment can attenuate pyroptosis and its signaling pathway that can be used as an adjuvant with hypoglycemic drugs in diabetic cardiomyopathy." (PMID 34685620, 2021). "It is unknown whether BMP-7 treatment can attenuate inflammatory cells, pyroptosis, inflammation, adverse cardiac remodeling, and enhances neovascularization, ultimately improving diabetic cardiomyopathy." (PMID 34685620, 2021). "BMP-7 treatment against inflammasome formation showed a significant reduction (p < 0.001) in the expression of TLR4 and NLRP3 as compared to the diabetic cardiomyopathy group." (PMID 34685620, 2021). "However, treatment with BMP-7 attenuates the expression of TLR4 (p = 0.027) and NLRP3 (p = 0.033) compared to the STZ-induced diabetic cardiomyopathy." (PMID 34685620, 2021). "Interestingly, treatment with BMP-7 attenuated the increased expression of Nek7 (p = 0.038) and GBP5 (p = 0.01) compared to the diabetic group, suggesting that BMP-7 attenuates inflammasome protein regulators Nek7 and GBP5 prior to the initiation of NLRP3 upregulation in diabetic cardiomyopathy." (PMID 34685620, 2021). "Therefore, we hypothesized that BMP-7 can inhibit the NLRP3 inflammasome complex and their activator Nek7-GBP5, and the subsequent cascade of pyroptosis in diabetic cardiomyopathy." (PMID 34685620, 2021).